EGFR (epidermal growth factor receptor)
Diseases named in the same sentence as EGFR in open-access papers (continued):
Sharing a sentence is not in itself a finding about the gene and the disease.
non-small cell lung carcinoma (continued). "The activation of cancer-promoting factor EGFR can up-regulate the expression of IL-6, JAK1/STAT3 signaling pathway and deteriorate NSCLC (non-small cell lung cancer), which was the reason for drug resistance." (PMID 35433636, 2022). "In non-small cell lung cancer (NSCLC) cells, ZEB1-mediated suppression of E-cadherin can induce migration, invasion, and activation of the epidermal growth factor receptor (EGFR)." (PMID 35454770, 2022). "Gefitinib, an epidermal growth factor receptor tyrosine kinase inhibitor (EGFR-TKI), is a well-known drug used for the treatment of non-small cell lung cancer." (PMID 36547923, 2022). "While the role of the EGFR kinase in non-small cell lung cancer (NSCLC) is appreciated, control of EGFR signaling pathways through dephosphorylation by phosphatases is not as clear." (PMID 36054194, 2022). "Five biological processes and pathways were screened, namely the MAPK signaling pathways, non-small cell lung cancer, regulation of actin cytoskeleton, PI3K-Akt signaling pathway, and EGFR tyrosine kinase inhibitor resistance." (PMID 35311468, 2022). "With the exception of EGFR, all genes demonstrated increased TMB levels in the mutant group of the non-small cell lung cancer cohort." (PMID 36204371, 2022). "The second one is amivantamab-vmjw (Rybrevant®), which targets epidermal growth factor receptor (EGFR) and mesenchymal epithelial transition factor (MET) and can be used in the treatment of non-small cell lung cancer (NSCLC)." (PMID 36077623, 2022). "In non-small cell lung cancer (NSCLC), exosomal lncRNA SOX2 overlapping transcript (SOX2-OT) secreted from NSCLC cells boosts M2 polarization, thus increasing EGFR-TKI resistance by targeting the miR-627-3p/SMADs pathway." (PMID 36612282, 2022). "For example, erlotinib, an epidermal growth factor receptor (EGFR) tyrosine kinase inhibitor, has shown synergistic effects when combined with anti-VEGF therapies, mainly in patients with advanced non-small cell lung cancer and colorectal cancer." (PMID 36324128, 2022). "Nevertheless, studies about targeting EGFR and STAT3 in glioblastoma, non-small-cell lung cancer, and pancreatic cancer exhibit promising therapeutic efficacy." (PMID 34298665, 2021). "Studies showed that long-term exposure to EGFR-TKIs activated TGF-β/Smad signaling and promoted the EMT phenotype in non-small cell lung cancer." (PMID 34335928, 2021). "Epidermal growth factor receptor (EGFR) genotyping, a critical examen for the treatment decisions of patients with non-small cell lung cancer (NSCLC), is commonly assayed by next-generation sequencing (NGS), but this global approach takes time." (PMID 34898548, 2021). "Erlotinib and dacomitinib are inhibitors of the epidermal growth factor receptor (EGFR) tyrosine kinase and are used to treat non-small cell lung cancer, pancreatic cancer, and several other cancer types." (PMID 34252346, 2021). "Erlotinib inhibits the tyrosine kinase of the epidermal growth factor receptor (EGFR) and has been used for a couple of years in the treatment of non-small cell lung cancer (NSCLC)." (PMID 34451842, 2021). "In the present study, exosomes in the serum of five patients with non-small cell lung cancer (NSCLC) were isolated before and after EGFR-TKIs resistance, and the circRNA expression profile was screened using a circRNA microarray." (PMID 33952725, 2021). "Apart from EGFR, KRAS, EML4-ALK, ERBB2, BRAF, and PIK3CA participate in the pathogenesis of non-small cell lung cancer." (PMID 34575089, 2021). "In vitro studies also showed that the fast growth of non-small cell lung cancer (NSCLC) and leukemia depends on the high activity of SOD1, which controls the oncogenic KRAS and EGFR pathways, as well as other cancer cells and xenograft tumors." (PMID 35011380, 2021). "Dimers of EGFR:HER2 and HER2:HER3 are known to drive the oncogenic signaling in breast and non-small cell lung cancers." (PMID 33800723, 2021).
non-small cell lung carcinoma (continued). "Epidermal growth factor receptor (EGFR) is an anticancer drug target for a number of cancers, such as non-small cell lung cancer." (PMID 34322025, 2021). "Glioblastoma, head and neck squamous cell carcinoma, esophagogastric adenocarcinoma and non-small cell lung cancer were the top four tumors with the highest alteration frequencies of LANCL2 and EGFR." (PMID 34461927, 2021). "Herein, we present a 58-year-old lady with advanced non-small cell lung cancer (NSCLC) ALK-negative, EGFR wild, and PD-L1 immune histochemistry (IHC) strongly positive in 95% of tumor cells, on ongoing treatment with Pembrolizumab as a first-line monotherapy." (PMID 33070259, 2021). "In this scenario, it is known that the epidermal growth factor receptor (EGFR) overexpression correlates with poor prognosis in many types of malignancies, including non-small cell lung cancer (NSCLC)." (PMID 34943180, 2021). "The findings revealed that three Nitroglycerin genes (EGFR, HRAS and MAPK3) were found to be common in 4 types of cancers viz Bladder cancer, Endometrial cancer, Melanoma and Non-small cell lung cancer." (PMID 34764329, 2021). "Exposure of the coculture of human lung non-small cell lung cancer cell line A549 and human fetal lung fibroblast HFL1 cells to the epidermal growth factor receptor EGFR-targeted drug gefitinib showed A549 cell resistance." (PMID 34683950, 2021). "Another top-scoring miRNA, miR-19b, is known to enhance proliferation and apoptosis resistance via the EGFR signaling pathway by targeting PP2A and BIM in non-small cell lung cancer." (PMID 33430103, 2021). "AhR, activated by kynurenine-tryptophan metabolized product by TDO2, bypasses EGFR to retrieve PI3K/AKT and MEK/ERK pathway leading to resistance to tyrosine kinase inhibitors in non-small cell lung cancer." (PMID 34174844, 2021). "The results indicate that the dual inhibition of EGFR and HER2 (human epidermal growth factor receptor 2) by afatinib, used for the treatment of non-small cell lung carcinoma (NSCLC), makes cells sensitive to radiation and reduces cell invasiveness." (PMID 34094980, 2021). "In non-small cell lung cancer (NSCLC), an up-regulated MIR31HG activates the EGFR/AKT cascade resulting in resistance to Gefitinib." (PMID 34445087, 2021). "In a cohort of 45 non-small cell lung cancer (NSCLC) patients, the positive rate of CellSearch was only 33%, and the enrichment based on EGFR/HER3 was 37.8%." (PMID 34798902, 2021). "CDR1as acts as miR-7 sponges to upregulate targets of miR-7 including EGFR, CCNE1, and PIK3CD in non-small-cell lung cancer." (PMID 34221006, 2021). "A clinical trial reported that erlotinib, an EGFR inhibitor approved by the Food and Drug Administration, decreased serum CCL2 levels in non-small-cell lung cancer (NSCLC) patients." (PMID 34386431, 2021). "The possibility of molecular testing, including epidermal growth factor receptor (EGFR), anaplastic lymphoma kinase (ALK), and programmed death ligand 1 (PD-L1), was identified with non-small cell lung cancer (NSCLC) tissue obtained using ENB." (PMID 34441366, 2021). "Lung tumor models are mainly cell cultures and cocultures of human non-small-cell lung cancer cells (A549), human fetal lung fibroblasts (HFL1), and targeted epidermal growth factor receptor (EGFR)." (PMID 34567763, 2021). "To investigate the role of ZNRF1 in EGFR signaling, we depleted expression of the ZNRF1 gene in A549 non-small cell lung cancer cells by lentivirus-mediated small hairpin RNA (shRNA) transduction." (PMID 33996800, 2021). "DDR, DNA damage response; EGFR, epidermal growth factor receptor; ER, estrogen receptor; HER2, human epidermal growth factor receptor 2; NSCLC, non-small-cell lung cancer; PARP, poly (ADP-ribose) polymerase; PR, progesterone receptor." (PMID 34068774, 2021).
non-small cell lung carcinoma (continued). "The transformation of non-small cell lung cancer to small cell lung cancer (SCLC) is one of the major resistant mechanisms, especially patients with epidermal growth factor receptor mutant lung adenocarcinoma." (PMID 34696545, 2021). "Advanced non-small-cell lung cancer (NSCLC) patients with EGFR T790M-positive tumours benefit from osimertinib, an epidermal growth factor receptor-tyrosine kinase inhibitor (EGFR-TKI)." (PMID 33741979, 2021). "Quick and reliable testing of EGFR and KRAS is needed in non-small cell lung cancer (NSCLC) to ensure optimal decision-making for targeted therapy." (PMID 34344387, 2021). "KLK6 regulated the proliferation and apoptosis of non-small-cell lung cancer cells via cleavage and activation of PAR2, which in turn activated the ligand-dependent epidermal growth factor receptor (EGFR) pathway." (PMID 34439122, 2021). "To demonstrate the relationship between genetic ancestry and somatic features, we focused on 2900 non-small cell lung cancer (NSCLC) patients with somatic, non-synonymous SNVs in the EGFR gene, which are known to have higher frequencies in Asians." (PMID 34749793, 2021). "For example, in non-small-cell lung carcinoma (NSCLC), EGFR tyrosine kinase inhibitors (EGFR-TKI) are used as treatment, but in some cases, EGFR-TKI resistance is detected within one year of drug administration." (PMID 34503137, 2021). "EGFR (epidermal growth factor receptor) inhibitors Erlotinib, Gefitinib and Afatinib, as well as Osimertinib, which targets the T970M mutant EGFR, have been approved for use in non-small-cell lung cancers." (PMID 34461089, 2021). "Immune checkpoint blockade (ICB) with checkpoint inhibitors has led to significant and durable response in a subset of patients with advanced stage EGFR and ALK wild-type non-small cell lung cancer (NSCLC)." (PMID 34208113, 2021). "In non-small cell lung cancer, IGF1R hyperactivity is related to acquired resistance to erlotinib, and simultaneous inhibition of EGFR and IGF1R is effective to prevent and also to overcome erlotinib resistance." (PMID 32796636, 2020). "In non-small cell lung cancer (NSCLC), the EGFR inhibitor gefitinib can achieve remarkable responses, but also induce tetraploidization which leads to p38 mediated drug resistance." (PMID 32046099, 2020). "Based on these results, it is required to conduct clinical tests on patients using EGFR-TKI, including patients with non-small cell lung cancer, as soon as possible." (PMID 32252690, 2020). "Cetuximab is an intravenously administered epidermal growth factor receptor (EGFR) inhibitor used to treat advanced colorectal cancer, head and neck squamous cell carcinoma, pancreatic cancer, and less frequently, non-small cell lung cancer." (PMID 32421085, 2020). "In non-small-cell lung cancer (NSCLC), the expression of TIPE is downregulated via a decrease in EGFR levels and an increase in SNX (a key regulator of EGFR transporters) levels, which further inhibits ECL- and IGF-1-stimulated NSCLC cell migration." (PMID 33718119, 2020). "A phase 1 trial using miR-16 mimic incorporated with epidermal growth factor receptor (EGFR) targeting antibody called TargomiR, was used for patients with either recurrent malignant pleural mesothelioma or non-small cell lung cancer." (PMID 33050637, 2020). "Contrary to this result, it has been reported that double inhibition of the EGFR and the FGFR in non-small cell lung cancer inhibit the survival and expansion of drug-resistant cells with EGFR mutations over a long period of time." (PMID 33092268, 2020). "Metformin interference with the ERK-NFkB axis has been shown to attenuate the resistance of non-small cell lung cancer (NSCLC) cell lines to both gefitinib and a third-gen epidermal growth factor receptor (EGFR) tyrosine-kinase-inhibitors (TKI)." (PMID 33182253, 2020).
non-small cell lung carcinoma (continued). "Mitochondrial EGFR also induces mitochondrial fission through inhibition of MFN1 and enhances energy production and cell motility to promote metastasis of non-small-cell lung cancer." (PMID 33019722, 2020). "Moreover, tumour shrinkage with targeted therapies may be delayed or absent, even if the drug is biologically efficient and some tyrosine-kinase inhibitors have been shown to provide patient benefit even after RECIST-defined progression, such as EGFR inhibitors in non-small cell lung cancer." (PMID 32224911, 2020). "The National Comprehensive Cancer Network (NCCN) guidelines recommend “broad molecular profiling”, including BRAF, ERBB2 (HER2), MET, RET, NTRK, and ROS1, in addition to EGFR and ALK for metastatic non-small cell lung cancer (NSCLC)." (PMID 32375398, 2020). "It has been reported that increased miR-146a suppresses the expression of EGFR, ERK1/2 and K-ras genes, resulting in the inhibition of cell migration, invasion and proliferation of pancreatic cancer and non-small cell lung cancer cells." (PMID 33248456, 2020). "Erlotinib is a specific inhibitor of epidermal growth factor receptor (EGFR) tyrosine kinase, which is given for locally advanced or metastatic non-small cell lung cancer treatment." (PMID 32703314, 2020). "Existing evidence has indicated that epidermal growth factor receptor (EGFR) is a vital participant in a variety of cancers, like non-small cell lung cancer and ovarian cancer." (PMID 32231464, 2020). "On 18 October 2016, the FDA approved atezolizumab for the treatment of people with metastatic non-small-cell lung cancer (NSCLC) with progression on platinum-based chemotherapy, and in progression on targeted therapy in patients with EGFR or ALK abnormalities." (PMID 32245016, 2020). "Acquired EGFR resistance continues to be a topic of investigation, and SHP2 has been studied as a target in patients with EGFR resistance in non-small cell lung cancer (NSCLC)." (PMID 33238500, 2020). "We also demonstrated that both vorinostat and VPA downregulate EGFR protein expression mainly by increasing protein degradation in HNSCC and non-small cell lung cancer cell lines and tumor primary cultures." (PMID 33015030, 2020). "Various EMT signatures have been shown to predict resistance to epidermal growth factor receptor (EGFR) or phosphatidylinositol 3-kinase (PI3K) inhibitors in clinical samples and cell lines derived from non-small-cell lung cancer patients." (PMID 32509584, 2020). "Non-small cell lung cancer (NSCLC) is known to have poor patient outcomes due to development of resistance to chemotherapy agents and the EGFR inhibitors, which results in recurrence of highly aggressive lung tumors." (PMID 32170113, 2020). "Aberrations in human epidermal growth factor receptor 2 (HER-2, ERBB2) have emerged as oncogenic drivers and therapeutic targets in 1–4% of non-small cell lung cancer (NSCLC) and up to 6% of EGFR/KRAS/ALK-negative lung adenocarcinoma (LUAD)." (PMID 32477948, 2020). "Activating mutations in the epidermal growth factorreceptor gene occur as early cancer-driving clonal events in a subset of patients with non-small cell lung cancer (NSCLC) and result in increased sensitivity to EGFR-tyrosine-kinase-inhibitors (EGFR-TKIs)." (PMID 31266248, 2019). "Despite the dramatic efficacy of erlotinib, an EGFR tyrosine kinase inhibitor (TKI), most of non-small cell lung cancer (NSCLC) patients ultimately acquire resistance to this agent." (PMID 31759360, 2019). "In non-small cell lung cancer, IGF-1 treatment of erlotinib-inhibited cells increased IGF1R/EGFR heterodimerization, leading to mTOR-mediated synthesis of EGFR and survivin, which counteracted the antiproliferative effects of Erlotinib." (PMID 30729097, 2019).
non-small cell lung carcinoma (continued). "Moreover, high levels of EGFR suggest poor survival in non-small cell lung carcinoma (NSCLC) patients, whereas high coexpression of EGFR and Her2-neu (another member of the erbB receptor tyrosine kinase family) is associated with outright inferior survival." (PMID 31200451, 2019). "In up to 30% of non-small cell lung cancer (NSCLC) patients, the oncogenic driver of tumor growth is a constitutively activated epidermal growth factor receptor (EGFR)." (PMID 31323891, 2019). "In non-small-cell lung cancer (NSCLC) and head and neck squamous cell carcinoma (HNSCC), activated EGFR pathways and downstream MEK/ERK signalling promote AXL mRNA expression through the JUN transcription factor." (PMID 31684958, 2019). "Epidermal growth factor receptor (EGFR), an oncogenic receptor tyrosine kinase, plays a key role in the development and progression of non-small-cell lung cancer (NSCLC)." (PMID 31196210, 2019). "The recent confirmatory AURA3 study included the patients with T790M-positive non-small-cell lung carcinoma (NSCLC), who had progressed after treatment with at least one EGFR kinase inhibitor." (PMID 31423385, 2019). "Epidermal growth factor receptor (EGFR) is crucial for the development and proliferation of multiple cancers, including colorectal carcinoma, non-small cell lung cancer, and PCa." (PMID 30975171, 2019). "Epidermal growth factor receptor (EGFR) is a well characterized therapeutic target to treat colorectal carcinoma and non-small cell lung cancer." (PMID 30975171, 2019). "On the other hand, in non-small cell lung cancer (NSCLC), a staggering ≈60% of the tumors had alterations in chief “driver oncogenes” including EGFR, BRAF, and KRAS combined." (PMID 31426419, 2019). "For non-small cell lung cancer (NSCLC), numerous clinical trials have demonstrated intracranial activity for inhibitors of EGFR and ALK." (PMID 31803366, 2019). "In non-small cell lung cancer, ESR1 can be combined with EGFR, showing enhanced antiproliferation effects." (PMID 31905767, 2019). "In non-small cell lung cancer, BMS-690514, an inhibitor of human EGFR and vascular EGFR, induces G1 cell cycle arrest and stimulates caspase-dependent apoptosis through downregulation of HSP40 and other HSPs." (PMID 31878360, 2019). "Patients with cancers, including non-small cell lung cancers (NSCLC), have been shown to response to EGFR-tyrosine kinase inhibitors (EGFR-TKIs) and anti-EGFR antibodies." (PMID 31527477, 2019). "In non-small cell lung cancer Apatinib reverses the drug resistance to gefitinib because of different mechanisms: synergistic effect on VEGFR2 and EGFR signaling pathways; or due to Warburg effect when a high rate of glycolysis exhausts the tumor growth." (PMID 31570733, 2019). "Despite progress in targeting epidermal growth factor receptor-mutant (EGFRm) non-small cell lung cancer (NSCLC), acquired resistance to EGFR tyrosine kinase inhibitors (TKIs) is inevitable." (PMID 30880334, 2019). "In non-small-cell lung carcinoma (NSCLC), miR-33a decreases expression of METTL3, thereby attenuating expression of target genes EGFR, TAZ and DNMT3A and suppressing NSCLC cell proliferation." (PMID 31801551, 2019). "In non-small cell lung cancer cells, MET overexpression increased EGFR downstream signaling and the combined use of dual EGFR/HER2 and MET tyrosine kinase inhibitors resulted in a maximal growth inhibition." (PMID 30227653, 2018). "For example, the three genes KRAS, EGFR, and ERBB2(HER2), which are found in the non-small cell lung cancer (NSCLC) signaling network, are key biomarkers." (PMID 29912931, 2018). "Epidermal growth factor receptor (EGFR), usually being overexpressed in many cancers, such as non-small-cell lung cancer and colorectal and breast cancers, has drawn scientists' attention early." (PMID 30406002, 2018). "The pathway enrichment suggested that they involved in EGFR-TKI resistance and non-small cell lung cancer pathways, which directly affect EGFR-TKI resistance." (PMID 30400936, 2018).